SLC6A14 (solute carrier family 6 member 14)
Description:
Amino acid transporter that plays an important role in the absorption of amino acids in the intestinal tract. Mediates the uptake of a broad range of neutral and cationic amino acids (with the exception of proline) in a Na(+)/Cl(-)-dependent manner. Transports non-alpha-amino acids such as beta-alanine with low affinity, and has a higher affinity for dipolar and cationic amino acids such as leucine and lysine. Can also transport carnitine, butirylcarnitine and propionylcarnitine coupled to the transmembrane gradients of Na(+) and Cl(-).
Synonyms: BMIQ11
Tractability: Small molecule: a high-quality ligand is known; it belongs to a druggable protein family. Antibody: its Gene Ontology location is reachable by antibodies, with high confidence; UniProt places it where antibodies can reach, with medium confidence; UniProt predicts a signal peptide or a membrane-spanning region; the Human Protein Atlas places it where antibodies can reach.
Gene: Protein-coding gene on chromosome X (116,436,606 to 116,461,458, forward strand). Ensembl gene ENSG00000268104.
Subcellular location: Membrane; Apical cell membrane
Subcellular location (Human Protein Atlas): Primary cilium; Primary cilium tip; Vesicles; Mitochondria; Plasma membrane
Pathways (Reactome):
Transport of small molecules: Amino acid transport across the plasma membrane; SLC-mediated transport of neurotransmitters
Disease: Variant SLC6A14 may confer susceptibility towards obesity
Gene Ontology:
Molecular function: (R)-carnitine transmembrane transporter activity; alanine transmembrane transporter activity; aromatic amino acid transmembrane transporter activity; beta-alanine transmembrane transporter activity; branched-chain amino acid:sodium symporter activity; neutral, basic amino acid:sodium:chloride symporter activity; amino acid transmembrane transporter activity; transmembrane transporter activity
Biological process: (R)-carnitine transmembrane transport; alanine transport; amino acid import across plasma membrane; beta-alanine transport; response to toxic substance; amino acid transmembrane transport; amino acid transport; glycine import across plasma membrane; neurotransmitter transport; sodium ion transmembrane transport; aromatic amino acid transport; branched-chain amino acid transport; chloride transport
Cellular component: extracellular exosome; vesicle; apical plasma membrane; membrane; plasma membrane
Homologues: Orthologues: chimpanzee SLC6A14 (99% identical), macaque SLC6A14 (97% identical), rabbit SLC6A14 (88% identical), Caenorhabditis elegans snf-6 (31% identical). Paralogues in human: SLC6A5 (49% identical), SLC6A7 (43% identical), SLC6A9 (41% identical), SLC6A3 (39% identical), SLC6A6 (39% identical), SLC6A2 (38% identical), SLC6A8 (38% identical), SLC6A11 (38% identical), SLC6A12 (38% identical), SLC6A13 (37% identical), SLC6A4 (36% identical), and 6 more.
Diseases named in the same sentence as SLC6A14 in open-access papers:
SLC6A14 is named in the same sentence as 54 diseases in open-access papers, as found by Europe PMC text mining. Sharing a sentence is not in itself a finding about the gene and the disease. The quoted sentences say what the papers report.
breast cancer (29 papers, 2016 to 2025). A primary or metastatic malignant neoplasm involving the breast. "With this small molecule, published reports have demonstrated the therapeutic utility of SLC6A14 blockade in the treatment of multiple tumor types that are associated with upregulation of this transporter: breast cancer, pancreatic cancer, and colon cancer." (PMID 33806675, 2021). "Functional studies have shown that the downregulation of SLC6A14 observed in endocrine therapy (ER + breast cancer standard of care)-resistant cells is associated with an increase of miR-23b-3p." (PMID 32166393, 2020). "The SLC6A14 gene has been linked to several diseases (e.g., obesity, ulcerative colitis, colon cancer, breast cancer, and cervical cancer)." (PMID 33302555, 2020). "In this regard it is noteworthy that knockout of Slc6a14, which encodes a transporter for neutral amino acids including tryptophan, the precursor of 5-HT, compromises mammary tumorigenesis in a mouse model of breast cancer." (PMID 28404880, 2017). "In this regard it is noteworthy that knockout of Slc6a14, which encodes a transporter for neutral amino acids including tryptophan, the precursor of 5-HT, compromises mammary tumorigenesis in mouse models of breast cancer." (PMID 27447971, 2016). "Therefore, the upregulation of mitochondria fusion and oxidative phosphorylation contributes to plasticizer‐associated early onset of breast cancer in a SLC6A14‐dependent manner, and targeting SLC6A14 is revealed as a potential therapeutic strategy for EOBC patients." (PMID 40959920, 2025). "Furthermore, SLC6A14 enhances the growth of ER-positive breast cancer in spontaneous mouse models of breast cancer; this mechanism may be associated with mTOR signaling." (PMID 29562706, 2018). "BCH and α-methyl-D,L-tryptophan are system B0,+ inhibitors, which can inhibit CAA (arginine) and neutral amino acid (leucine) transport by the system B0,+ transporter protein, ATB0,+ (SLC6A14) when expressed in xenopus oocytes or breast cancer cells." (PMID 40498714, 2025). "The expression of SLC6A14 in tumor tissues was higher in younger breast cancer patients with an odds ratio of 3.896 (p‐value = 0.025) and negatively correlated with the age at diagnosis." (PMID 40959920, 2025). "Global transcriptomic analysis of endocrine therapy-resistant breast cancer cells revealed that SLC6A14 expression is downregulated under the control of increased miR-23b-3p expression, resulting in increased aspartate and glutamate uptake." (PMID 39973065, 2025). "The transmembrane transporter SLC6A14 has the highest expression in luminal subtypes of breast cancer." (PMID 39852119, 2024). "A link was established between SLC6A14 expression and positive ER expression both in primary breast cancer cells and in the MCF cell line." (PMID 39852119, 2024). "Researchers have shown that SLC7A5 and SLC6A14 are upregulated in several cancers of epithelial origin, including breast cancer." (PMID 37238741, 2023). "α-MT has been successfully applied to SLC6A14-positive breast cancer xenograft models and significantly suppresses tumor growth." (PMID 35907820, 2022). "SLC6A14 knockout mice showed delays in the development of mammary tumors when crossed with the polyoma middle T oncoprotein mouse breast cancer model." (PMID 35865664, 2022). "SLC6A14 expression is too low to be detected in healthy tissues but is significantly increased in pancreatic, cervical, and breast cancers." (PMID 35907820, 2022). "Published reports have demonstrated the therapeutic utility of α-methyl-l-tryptophan as a fairly selective inhibitor of SLC6A14 in the treatment of breast cancer, pancreatic cancer, and colon cancer." (PMID 36578780, 2022). "The role of SLC6A14 in supply of amino acids to cancer cells appears confirmed as SLC6A14 knockout leads to a decrease in tumour growth in mouse models of estrogen receptor positive breast cancer and pancreatic cancer." (PMID 36291613, 2022).
breast cancer (continued). "SLC6A14 has been shown to be such a cancer-specific amino acid transporter: it is highly expressed in estrogen receptor-positive (ER+) breast cancers and pancreatic cancer, but low in normal tissues." (PMID 35907820, 2022). "α-MT, a small-molecule inhibitor targeting SLC6A14, has been successfully employed to block the function of SLC6A14 in a breast cancer xenograft model." (PMID 35907820, 2022). "Several reports have shown marked upregulation of SLC6A14 in many types of solid tumors, including colon cancer, cervical cancer, estrogen receptor-positive breast cancer, and pancreatic cancer." (PMID 33806675, 2021). "SLC6A14 is a direct target for estrogen/ER, thus providing the molecular basis for its up-regulation in ER+ breast cancer." (PMID 34704597, 2021). "The experiments were performed with cell lines characterized by a high level of SLC6A14, i.e., the endogenous transporter in breast cancer MCF-7 cells, and the overexpressed transporter in HEK293 cells." (PMID 34359969, 2021). "The high expression of SLC6A14 is prognostic and unfavorable in pancreatic cancer, while in breast cancer it is expressed in estrogen receptor positive cells." (PMID 33195271, 2020). "SLC6A14 is significantly upregulated in tissues from cervical, colorectal, pancreatic, and estrogen receptor-positive (ER+) breast cancer." (PMID 32166393, 2020). "When the Slc6a14 KO mice were crossed with model mouse lines developing a spontaneous breast cancer, the development of tumor was significantly delayed and its growth was decreased on Slc6a15–/– background." (PMID 33195271, 2020). "In ER+ breast cancer, high expression of SLC6A14 mRNA has been correlated with a better survival among patients." (PMID 32166393, 2020). "Using MCF-10A, a non-tumorigenic breast epithelial cell line, for data normalization, we confirmed the high variability in SLC6A14 expression in different breast cancer cell lines." (PMID 33400734, 2020). "To evaluate the expression levels of SLC6A14 in tumor samples we used breast cancer as a study model." (PMID 33400734, 2020). "By combining human breast cancer data analysis and a broad panel of breast cancer cell lines, we show that SLC6A14 is expressed at highly heterogenous levels." (PMID 33400734, 2020). "Next, we assessed by RT-qPCR SLC6A14 transcript levels in a panel of breast cancer cell lines representative of five well-defined breast cancer subtypes." (PMID 33400734, 2020). "Treatment of ER-positive breast cancer cells with α-methyl-dl-tryptophan (α-MT), a selective blocker of SLC6A14, leads to amino acid deprivation, inhibition of the mTOR pathway, activation of autophagy, and induction of cancer cell apoptosis." (PMID 29562706, 2018). "SLC6A14 is highly expressed in ER-positive breast cancer, as demonstrated using both primary breast cancer tissues and breast cancer cell lines." (PMID 29562706, 2018). "Many cancers, particularly those of epithelial origin such as cervical, pancreatic ductal adenocarcinoma and breast cancer upregulate SLC6A14 to take advantage of its high capacity for glutamine uptake." (PMID 28350329, 2017). "The amino acid transporter SLC6A14 is directly upregulated by estrogen/ER activity in ER+ breast cancers." (PMID 28350329, 2017). "In spontaneous mouse models of breast cancer, enhanced SLC6A14 expression promotes the growth of ER-positive breast tumors, while SLC6A14 gene knockout mice exhibit breast tumors with amino acid starvation, weakened mTOR signaling, and reduced cell proliferation." (PMID 39973065, 2025). "Other than genetic deficiency, exposure to an environmentally hazardous plasticizer DEHP was demonstrated to contribute to the early onset of breast cancer through augmentation of cancer stemness relying on SLC6A14‐dependent mitochondria dynamics in this study." (PMID 40959920, 2025). "These clinical findings support that SLC6A14 upregulation by DEHP may contribute to cancer stemness and be associated with the early onset of breast cancers." (PMID 40959920, 2025).
breast cancer (continued). "Furthermore, SLC6A14's oncogenic functions in gastric cancer and breast cancer have been documented." (PMID 38267509, 2024). "Molecular characterization of SLC6A14 in transgenic models of breast cancer showed that CCAAT-enhancer binding protein homologous protein and asparagine synthetase were upregulated and might be responsible for the poor growth of tumors." (PMID 35907820, 2022). "Furthermore, the deletion of Slc6a14 in mice interferes with the growth of spontaneous mammary tumors." (PMID 34704597, 2021). "Indeed, overexpression of SLC6A14 has been reported in various cancers (e.g., colon cancer, breast cancer, pancreatic cancer, and cervical cancer)." (PMID 33302555, 2020). "In this study, we extend the knowledge about SLC6A14 function by exploiting for the first time the combination of metabolic stress coupled to the transporter inhibition and elucidate the molecular responses elicited in breast cancer cells." (PMID 33400734, 2020). "A global transcription analysis reveals downregulation of SLC6A14 and an enhanced expression of miR-23b-3p in endocrine therapy resistant breast cancers, what correlates with a prosurvival autophagy and a selective upregulation of SLC1A2 and results in an increased uptake of Glu and Asp." (PMID 33195271, 2020). "SLC6A14 is a target of the ER, and this may explain the relationships between SLC6A14 and ER status in breast cancer." (PMID 29562706, 2018). "However, silencing certain SLC genes (e.g., SLC1A5 in breast cancer and SLC6A14 in colorectal cancer) can significantly impair L‐serine uptake, leading to metabolic disruption, as compensatory changes in other SLCs fail to sustain intracellular L‐serine levels." (PMID 40971730, 2025). "In breast cancer mouse models, SLC6A14 knock out mice showed a marked delay in tumour formation and tumour size, and analysis of the tumour material revealed evidence of amino acid starvation in the slc6a14-/- mice suggesting a key role from SLC6A14 in both tumour development and growth." (PMID 32024004, 2020). "The selective blocker of SLC6A14, α-methyl-dl-tryptophan (α-MT), when used in vitro on ER-positive MCF7 breast cancer cells, can induce amino acid deprivation, inhibit mTOR, and activate autophagy." (PMID 39973065, 2025). "It has been demonstrated that SLC1A5, SLC6A14, SLC7A11, SLC3A1, SLC7A5, SLC38A2, and SLC38A5 are significantly expressed in breast cancer cells." (PMID 39973065, 2025). "Dual targeting of SLC6A14 with SLC25A15, SLC12A4, SLC1A5 and SLC38A5 also reduced growth in MCF7 and MDA-MB-231 human breast cancer cell lines." (PMID 38066114, 2023). "SLC1A5, SLC3A2, SLC7A5, and SLC6A14 may be promising biomarkers for BC [breast cancer] diagnosis and may represent potential therapeutic targets for these patients”." (PMID 37627015, 2023). "Human breast cancer cells, including MCF-7, were shown to express LAT1 (SLC7A5) and LAT2 (SLC7A8); however, only SLC6A14 requires chloride ions for its activity." (PMID 34359969, 2021). "We first examined primary tumor specimens from patients with ER+ breast cancer and TNBC for expression of SLC6A14 and SLC38A5." (PMID 34704597, 2021). "Grouping the samples based on the major breast cancer subtypes defined by the PAM50 gene expression signature, we observed the highest levels of SLC6A14 expression in the basal-like and in the normal-like subtypes." (PMID 33400734, 2020). "Inhibition of HSP70 and HSP90 decreased the amount of SLC6A14 not only after its overexpression, but also in MCF7 estrogen receptor positive breast cancer cell line." (PMID 33195271, 2020). "The expression of SLC6A14 also exhibited a positive correlation with the level of SOX2 in tumors with an odds ratio of 4.40 (p‐value = 0.012) and the hair level of DEHP in breast cancer patients." (PMID 40959920, 2025). "Therefore, the estrogen receptor-positive breast cancer cell line MCF-7, known to express SLC6A14, was selected." (PMID 34359969, 2021).
breast cancer (continued). "The Na+/Cl−-coupled broad-selective amino acid transporter SLC6A14 is expressed ER+ breast cancer cell lines but not in TNBC cell lines." (PMID 34704597, 2021). "We analyze the pattern of transcriptional changes in a panel of breast cancer cell lines upon metabolic stress and found that SLC6A14 expression levels are increased in the absence of methionine." (PMID 33400734, 2020). "SLC6A14 expression was shown to be regulated by estrogen which explains its specific increased expression in ER+ but not in ER- breast cancer." (PMID 32166393, 2020). "SLC6A14, which is also known as ATB (0,+), is an amino acid transporter that is found upregulated in ER+ breast cancer, could be a novel and effective pharmacological target for breast cancer treatment." (PMID 31052256, 2019). "In breast cancer, SLC1A5 and SLC6A14 are upregulated amino acid transporters that carry glutamines, and therefore glutamine metabolism may largely affect tumor biology." (PMID 29562706, 2018). "Some amino acid transporters, including SLC1A5, SLC6A14, SLC7A5, and SLC7A11, may be promising targets for the treatment of breast cancer since they modulate tumor growth, metastasis, treatment response, and prognosis of breast cancer." (PMID 29562706, 2018). "In previous studies, mice with deficiencies in SLC1A5, SLC6A14, and SLC7A11, which have been reported to be upregulated in breast cancer, were found to be viable and fertile and to have no abnormal phenotypes." (PMID 29562706, 2018). "According to the type of breast cancer (i.e., HER2+ or ER+), several amino acid transporters, such as SLC1A5, SLC6A14 and SLC7A5, were shown to have different expressions in BC tissue compared to controls." (PMID 37628869, 2023). "Furthermore, α-MT can inhibit tumor cell proliferation both in vitro and in vivo only in SLC6A14-positive breast cancer lines, but not in SLC6A14-negative breast cancer cell lines." (PMID 35907820, 2022).